KLF3-AS1 (KLF3 antisense RNA 1)
Synonyms: FLJ13197
Gene: Long non-coding RNA gene on chromosome 4 (38,594,512 to 38,664,952, reverse strand). Ensembl gene ENSG00000231160.
Diseases named in the same sentence as KLF3-AS1 in open-access papers:
KLF3-AS1 is named in the same sentence as 1 disease in open-access papers, as found by Europe PMC text mining. Sharing a sentence is not in itself a finding about the gene and the disease.
KLF3-AS1 shares sentences with these, for which no sentence is quoted: retinitis pigmentosa (1 paper).